COL12A1 (collagen type XII alpha 1 chain)
Diseases named in the same sentence as COL12A1 in open-access papers (continued):
Sharing a sentence is not in itself a finding about the gene and the disease.
cancer (50 papers, 2013 to 2025). A tumor composed of atypical neoplastic, often pleomorphic cells that invade other tissues. "COL12A1 mRNA and protein expression were positively associated with carboplatin AUC and paclitaxel AUC in all cancer cell lines, suggesting a relationship with both carboplatin and paclitaxel resistance." (PMID 40565351, 2025). "COL12A1 alters the structural components of the extracellular matrix by using some of the kinases, miRNAs, and transcription factors associated with cancer and by integrin binding and collagen binding." (PMID 37361568, 2023). "The different methods indicated COL12A1 was crucially related to cancer-associated fibroblast infiltration." (PMID 36900272, 2023). "The knocking down of COL12A1 decreased the proliferation and migration of cancer-associated fibroblasts (CAFs) and down-regulated the expression of CAF activation markers." (PMID 37700383, 2023). "Previous studies suggested that COL1A2 expression was up-regulated in multiple human carcinomas and abnormal increasing expression of COL12A1 was associated with a poor prognosis." (PMID 36776317, 2023). "YAP1 target COL12A1 (collagen type 12 alpha one chain) is an extracellular matrix protein and is shown to be associated with progressive and recurrent cancers in multiple solid tumors." (PMID 35407556, 2022). "Collagen type XII alpha 1 chain (COL12A1) is associated with human cancer progression." (PMID 36694230, 2023). "Moreover, COL12A1 mRNA expression and protein levels in cancer cell lines associated with carboplatin and paclitaxel resistance and increased COL12A1 expression in OVCAR-8 spheroids cisplatin-resistant cells also support a relationship with chemotherapy resistance." (PMID 40565351, 2025). "COL12A1 expression was much higher in cancer tissue than in para-cancer tissue as indicated by the qPCR results." (PMID 36900272, 2023). "In histologic grades, II/III/IV, much higher COL12A1 expression was observed than that in grade I (histologic grade in TCGA means the numeric value to express the degree of abnormality of cancer cells; it is a measure of differentiation and aggressiveness)." (PMID 36900272, 2023). "Meanwhile, the interleukin 6 (IL6), CXC chemokine Ligand-5 (CXCL5), and CXC chemokine Ligand-10 (CXCL10) expressions were inhibited, and the cancer-promoting effect was reversed by COL12A1 knockdown." (PMID 36900272, 2023). "JYQHD inhibited the development of GC cells by inhibiting cancer cell stemness via the ferroptosis pathway mediated by COL12A1." (PMID 37700383, 2023). "COL12A1 has attracted great attention because of its promising activities in cancers, since the over-expressed level of COL12A1 can be detected in multiple cancer." (PMID 37700383, 2023). "COL12A1, ferroptosis markers and cancer stemness markers including GXP4, SLC7A11, Sox2 and Oct4 were obviously weakened by JYQHD." (PMID 37700383, 2023). "The COL12A1 gene is associated with multiple disease prognoses and immune infiltration, and high COL12A1 expression in cancer tissues can promote disease development and progression." (PMID 36552219, 2022). "COL12A1 overexpression has been proven in several cancers, indicating its oncogenic role in human cancer." (PMID 34094925, 2021). "Utilizing CCK-8, Transwell and matrigel assays, overexpression of miR-1180-3p reduced cancer cell proliferation and mobility, but induced apoptosis, by targeting COL12A1." (PMID 34723759, 2021). "To totally evaluate the role of COL12A1 in multiple solid tumors, we used two TCGA CRC datasets to explore the expression levels of COL12A1 mRNA in cancers." (PMID 32356618, 2020). "Functional network analysis suggested that COL12A1 regulated integrin binding, collage binding, and extracellular matrix structural constituent via pathways involving some several cancer‐related kinases, miRNAs, and transcription factor." (PMID 32356618, 2020).
cancer (continued). "COL12A1, a gene encoding collagen type XII alpha 1 chain, is a typical collagen-organizer molecule involved in collagen cross-linking in the cancer microenvironment." (PMID 33381592, 2020). "The findings indicated that hypermethylation of COL12A1 promoter can inhibit COL12A1 in promoting cancer development." (PMID 32356618, 2020). "COL12A1, a gene encoding collagen type XII alpha 1 chain, is a typical collagen-organizer molecule involved in collagen cross-linking in cancer microenvironment." (PMID 31315643, 2019). "Our study firstly clarified that the enhancing migratory ability of cancer cells was interdependent between COL12A1 and IDO1." (PMID 31315643, 2019). "Module III represents CAFs expressing COL1A1, COL1A2, and COL3A1 enriched in the cancer regions, whereas module IV identifies a subset known as myofibroblasts (myCAFs) (COL12A1, THBS2) that mainly contribute to extracellular matrix remodeling and growth and metastasis of cancer cells." (PMID 40033360, 2025). "Cancer-associated fibroblasts (CAF) expressed well-known markers including FAP, COL1A1, COL10A1, MMP11, and CTHRC120,21, and other genes such as INHBA, SLC12A8, F2R, and COL12A1 in various organs." (PMID 38744958, 2024). "The highest expression of genes encoding Col1a1-2, Col3a1, Col4a1, Col4a2, Col5a1, Col5a2, Col6a1, Col8a1, Col9a3, Col10a1, Col12a1, Col14a1, Col15a1, Col16a1, Col18a1, and Col28a1 were detected in untreated tumors, whose landscapes were dominated by Krt8+ cancer cells." (PMID 39372930, 2024). "The cancer-promoting effect was reversed with COL12A1 knockdown." (PMID 36900272, 2023). "COL12A1 (collagen type XII α1 chain) is a member of the fibril-associated collagen family and has received increasing attention due to its essential roles in human cancer because its overexpression has been identified in several different cancer types." (PMID 34128694, 2021). "IDO-1 plays a crucial role in tumor metastasis in many cancer types, such as gastric cancer, and the increased expression of IDO-1 and expression of the core gene COL12A1 synergistically improve cancer cell invasion and metastasis via the MAPK transduction pathway." (PMID 34367975, 2021). "COL12A1, a gene encoding collagen type XII α 1 chain, is a typical molecule that regulates collagen expression and is involved in the formation of collagen in the cancer microenviroment." (PMID 34233716, 2021). "In addition, ECM components such as collagens including COL12A1 are thought to affect sensitivity of cancer cells to chemotherapeutics." (PMID 33924987, 2021). "Interestingly, correlation between COL12A1 expression and clinicopathological features including patients’ individual cancer stages and node metastasis status was analyzed using UALCAN." (PMID 32356618, 2020). "Of those related genes, COL12A1 is identified as the critical gene on promoting cancer migration." (PMID 31315643, 2019). "The novel findings suggested that both IDO1 and COL12A1 may be promising targets on anti-cancer treatment in GC." (PMID 31315643, 2019). "The high-throughput proteomics analysis revealed differential expressions of Acsl1, Plin1, Dbil5, Plin4, Col12a1, Col1a1, Col5a3, Col1a2, and Dcn, which are associated with the PPAR signaling pathway, protein digestion and absorption, and the protein glycan pathway in cancer." (PMID 36874004, 2023). "Hence, the hsa-miR-26b-5p-COL12A1 axis may be a potential pathway in mediating cancer progression of PDAC." (PMID 33027767, 2020). "Thus, we speculated that hypermethylation of COL12A1 promoter can inhibit the effect of COL12A1 on promoting cancer development and served as an evidence for early cancers’ diagnosis." (PMID 32356618, 2020). "High CXCL12 expression was observed in ESCC and BC, with mutually exclusive distribution from COL12A1, particularly in ESCC, highlighting these cancers as ideal models for CAFs subtype research." (PMID 41228323, 2025).
cancer (continued). "Our histopathological evidence has shown that COL12A1 and FN1 are expressed from stromal cells, THBS2, and VCAN from stromal and cancer cells, while ITGA2, LAMB3, and LAMC2 are expressed solely from the cancer cells." (PMID 34007003, 2021). "Among these proteins, the overexpression of MMP14, ITGA2, THBS2, COL1A1, COL3A1, COL11A1 and COL6A3 has been experimentally confirmed in PDAC, while that of COL12A1 and COL5A2 has been shown in other types of cancer." (PMID 34094925, 2021). "We also explored the predictive efficacy of the four proteins (COL12A1, THBS2, S100A8, and S100A9) in multi-cancer cohort composed of 115 plasma samples from 95 patients with treatment-naive patients with various cancer types and 20 HCs, and two public cohorts related to the non-malignant diseases." (PMID 38302471, 2024). "Some of these potential proteins (COL12A1, THBS2, S100A8, and S100A9) were reported to associate with other cancers and non-malignant diseases, which limited the clinical validity of the potential proteins in CRC." (PMID 38302471, 2024). "Moreover, PLOD3 and COL12A1 were related to the epithelial–mesenchymal transition (EMT) pathway, which is regarded as one of the core events that contribute to cancer metastasis." (PMID 34585630, 2021). "Minimal COL12A1 protein was present in HGSOC tissues at diagnosis, but COL12A1 protein levels (% positive pixels) were significantly increased in the cancer-associated stroma in patients 2, 3, and 4 but not in patient 1 relapse tissues compared to tissues at diagnosis." (PMID 40565351, 2025). "The overexpressed integrin α (ITGA) subfamily genes ITGA2 and ITGA3 are predicted to be involved in cancer-related pathways such as PI3K-Akt signaling pathway and FA interacting with ECM genes such as laminin (LAMB3, LAMA3, and LAMC2) and collagen (COL10A1, COL12A1)." (PMID 34262595, 2021). "Overall, we validated the consistency of up-regulation of the four proteins (COL12A1, THBS2, S100A8, and S100A9) was only observed in CRC but not in other cancer types; and the four proteins could achieve good performance in the diagnosis of CRC, but not other cancer types." (PMID 38302471, 2024).
myopathy (8 papers, 2015 to 2025). A disease of the muscle in which the muscle fibers do not function properly. "In 2014, a myopathy/anhydrotic ectodermal dysplasia (EDA)-like disease caused by heterozygous COL12A1 variants was reported." (PMID 35368668, 2022). "COL12A1 was associated with myopathy and the only association to a neurodegenerative disease is its decreased amount in the cervical spinal cord of patients with ALS." (PMID 26362251, 2015). "In addition, given the overall mild myopathic features, we surmise that some patients classified as hypermobile EDS might have COL12A1 pathogenic variants in whom the myopathy has gone unnoticed, as recently reported." (PMID 31509352, 2019). "In our series we report three patients (P4, P5, and P6) with biallelic COL12A1 variants who present with a similar milder disease, further establishing COL12A1‐related myopathy and expanding the phenotypic spectrum." (PMID 39923201, 2025). "Patients with dominant COL12A1‐related myopathies were characterized by history and clinical examination, muscle imaging, and genetic analysis." (PMID 31509352, 2019). "Except for variants in COL12A1, no disease‐causing variants in other known myopathy or connective tissue disease genes were detected." (PMID 31509352, 2019).
connective tissue disorder (5 papers, 2013 to 2025). A disease involving the connective tissue. "Noteworthy, the mutations in COL5A1, COL6A1, or COL12A1 cause connective tissue disorders in humans, altering fiber organization and mechanical properties, resulting in tissue fragility." (PMID 34575162, 2021).
infection (3 papers, 2020 to 2023). The state of being infected such as from the introduction of a foreign agent such as serum, vaccine, antigenic substance or organism. "Also, whereas collagen proteins were downregulated during infection of HFFF-TERTs, the same proteins were upregulated in THP-1s (COL1A1, COL1A2, COL3A1, COL5A1, and COL12A1)." (PMID 38065956, 2023).
heart disease (1 paper, 2020). "Five of these genes codes for proteins that are known to be involved in heart disease and three of these, COL12A1, THBS1 and HSP70 are of particular interest." (PMID 32878883, 2020).
metabolic disease (1 paper, 2023). A congenital disorder (due to inherited enzyme abnormality) or acquired (due to failure of a metabolically important organ) disorder resulting from an abnormal metabolic process. "COL12A1 is a key component of ECM, which takes part in the remodeling of adipose tissue in fatness and metabolic disease." (PMID 38275592, 2023).
COL12A1 also shares sentences with these, for which no sentence is quoted: esophageal squamous cell carcinoma (2 papers); lymphoma (2); melanoma (2); neurodegenerative disease (2); Ullrich congenital muscular dystrophy 2 (2); Arthritis (1); atherosclerosis (1); bladder urothelial carcinoma (1); cardiovascular disease (1); central nervous system lymphoma (1); channelopathies (1); cholangiocarcinoma (1); chondromyxoid fibroma (1); co-infection (1); colorectal (1); Corneal opacity (1); coronary heart disease (1); COVID-19 (1); developmental delay (1); Duchenne muscular dystrophy (1); glioma (1); heart failure (1); hepatoblastoma (1); hypertriglyceridemia (1); ischemia (1); leiomyoma (1); lung carcinoma (1); lymph node metastasis (1); medulloblastoma (1); metastatic tumors (1).
A further 13 diseases each share a sentence with COL12A1 in 1 paper.